TMEM47 (transmembrane protein 47)
Description:
Regulates cell junction organization in epithelial cells. May play a role in the transition from adherens junction to tight junction assembly. May regulate F-actin polymerization required for tight junctional localization dynamics and affect the junctional localization of PARD6B. During podocyte differentiation may negatively regulate activity of FYN and subsequently the abundance of nephrin (By similarity).
Synonyms: BCMP1; TM4SF10; DKFZP761J17121; DKFZp564E153; VAB-9
Tractability: Antibody: its Gene Ontology location is reachable by antibodies, with high confidence; UniProt predicts a signal peptide or a membrane-spanning region. PROTAC: its protein half-life has been measured.
Gene: Protein-coding gene on chromosome X (34,627,075 to 34,657,285, reverse strand). Ensembl gene ENSG00000147027.
Subcellular location: Membrane; Cell junction, adherens junction
Subcellular location (Human Protein Atlas): Nuclear membrane
Gene Ontology:
Molecular function: protein binding
Biological process: cell-cell adhesion
Cellular component: plasma membrane; cell-cell junction; adherens junction; membrane
Homologues: Orthologues: chimpanzee TMEM47 (100% identical), macaque TMEM47 (100% identical), pig TMEM47 (100% identical), mouse Tmem47 (99% identical), rat Tmem47 (98% identical), tropical clawed frog tmem47 (91% identical), zebrafish tmem47 (82% identical), guinea pig TMEM47 (61% identical), Caenorhabditis elegans vab-9 (26% identical), Drosophila melanogaster CG45049 (24% identical). Paralogues in human: PERP (32% identical).
Diseases named in the same sentence as TMEM47 in open-access papers:
TMEM47 is named in the same sentence as 11 diseases in open-access papers, as found by Europe PMC text mining. Sharing a sentence is not in itself a finding about the gene and the disease. The quoted sentences say what the papers report.
breast carcinoma (3 papers, 2015 to 2023). "TMEM47 is significantly associated with the biological processes of aggressive breast cancer." (PMID 32793117, 2020). "These genes likely play critical roles in cancer progression because cBioPortal analysis revealed amplification and /or mutations of TMEM47, LYPD1 and SLITRK2 in a variety of cancers including breast cancer." (PMID 25926557, 2015). "SNP rs10522027 is found within the gene transmembrane protein 47 (TMEM47), which may be associated with the chemoresistance of breast cancer cells and hepatocellular carcinoma." (PMID 36979477, 2023). "In this dataset, TMEM47 also showed elevated expression in Basal and HER2+ breast cancers compared with luminal A and B breast cancers." (PMID 25926557, 2015). "TMEM47 displayed prognostic value in estrogen receptor and progesterone negative but not in estrogen receptor and progesterone receptor positive breast cancer (data not shown)." (PMID 25926557, 2015). "We next determined whether the expression of LYPD1, TMEM47 and/or SLITRK2 is enriched in a specific intrinsic subtype of breast cancer." (PMID 25926557, 2015).
brain tumors (2 papers, 2015 to 2021). "TMEM47 is consistently upregulated in vitro, ex vivo, in vivo (MP), and in the postmortem human SN and has been linked to neuronal development and/or brain tumors." (PMID 34494552, 2021). "TMEM47 and SLITRK2 are linked to neuronal development and/or brain tumors." (PMID 25926557, 2015).
hepatocellular carcinoma (2 papers, 2022 to 2023). A malignant tumor that arises from hepatocytes. "SNP rs10522027 is within the gene transmembrane protein 47 (TMEM47), which may be a useful biomarker for predicting the response to chemotherapy and a potential therapeutic target for overcoming hepatocellular carcinoma cell chemoresistance." (PMID 35610583, 2022).
thyroid cancer (2 papers, 2020 to 2024). "A recent study showed that TMEM47 is also screened as the prognostic signature for thyroid cancer and is beneficial to prognosis." (PMID 38186223, 2024).
alcohol dependence (1 paper, 2022). Physical and psychological dependence on alcohol. "We finally identify only one gene, TMEM47, statistically significantly associated with the alcohol dependence composite score (p value =2.32×10−6)." (PMID 35627212, 2022). "We applied the proposed methods to the MCTFR data and identified a gene, TMEM47, which is statistically significantly associated with the alcohol dependence composite score." (PMID 35627212, 2022). "That is to say, the point estimates are all less than 0.5, while the 95% HPDIs or CIs all contain 1, which means that the XCI pattern for TMEM47 on the alcohol dependence composite score may be the XCI-R or the XCI-E." (PMID 35627212, 2022). "However, although the four point estimates of γ for the gene TMEM47 on the alcohol dependence composite score are all smaller than 0.5, the corresponding 95% HPDIs or CIs all contain 1, which means that the XCI pattern for this gene may not be the XCI-S." (PMID 35627212, 2022).
Intellectual disability (1 paper, 2020). "A screening involving 16 affected patients revealed no TMEM47 implication, but a case of TMEM47 disruption has been linked to intellectual disability and language delay." (PMID 32767978, 2020).
TMEM47 also shares sentences with these, for which no sentence is quoted: cancer (1 paper); language delay (1); melanoma (1); skin cancer (1); tumor (1).